SLC27A3 (solute carrier family 27 member 3)
Description:
Mainly functions as an acyl-CoA ligase catalyzing the ATP-dependent formation of fatty acyl-CoA using LCFA and very-long-chain fatty acids (VLCFA) as substrates. Can mediate the levels of long-chain fatty acids (LCFA) in the cell by facilitating their transport across membranes (By similarity).
Synonyms: VLCS-3; ACSVL3; FATP3; MGC4365
Tractability: Antibody: UniProt predicts a signal peptide or a membrane-spanning region; its Gene Ontology location is reachable by antibodies, with medium confidence. PROTAC: ubiquitination databases record sites on it; its protein half-life has been measured.
Gene: Protein-coding gene on chromosome 1 (153,774,354 to 153,780,158, forward strand). Ensembl gene ENSG00000143554.
Subcellular location: Mitochondrion membrane
Subcellular location (Human Protein Atlas): Endoplasmic reticulum; Mitochondria
Pathways (Reactome):
Metabolism: Synthesis of very long-chain fatty acyl-CoAs
Gene Ontology:
Molecular function: long-chain fatty acid-CoA ligase activity; very long-chain fatty acid-CoA ligase activity; arachidonate-CoA ligase activity
Biological process: fatty acid transport; long-chain fatty acid metabolic process
Cellular component: membrane; mitochondrion; endoplasmic reticulum membrane; plasma membrane; mitochondrial membrane
Genetic constraint (gnomAD): Loss-of-function variants: 61 observed, 55.32 expected, observed/expected ratio (o/e) 1.1, 90% interval 0.9 to 1.37. The synonymous counts are far from expectation, so gnomAD's model fits this gene poorly and the ratio says little. Missense variants: 1,079 observed, 862.71 expected, observed/expected ratio (o/e) 1.25, 90% interval 1.19 to 1.32. Synonymous variants: 455 observed, 377.04 expected, observed/expected ratio (o/e) 1.21, 90% interval 1.12 to 1.3.
Homologues: Orthologues: chimpanzee SLC27A3 (99% identical), macaque SLC27A3 (95% identical), pig SLC27A3 (88% identical), guinea pig SLC27A3 (84% identical), rat Slc27a3 (84% identical), dog SLC27A3 (84% identical), mouse Slc27a3 (84% identical), rabbit SLC27A3 (67% identical), tropical clawed frog supt20hl1 (48% identical), Drosophila melanogaster Fatp3 (33% identical), Drosophila melanogaster Fatp1 (31% identical), Drosophila melanogaster Fatp2 (31% identical), and 21 more. Paralogues in human: SLC27A6 (40% identical), SLC27A5 (40% identical), SLC27A2 (39% identical), SLC27A4 (35% identical), SLC27A1 (35% identical), ACSL3 (17% identical), ACSL5 (17% identical), ACSL1 (17% identical), ACSL4 (16% identical), ACSL6 (16% identical), ACSBG1 (15% identical), ACSBG2 (14% identical).
Diseases named in the same sentence as SLC27A3 in open-access papers:
SLC27A3 is named in the same sentence as 36 diseases in open-access papers, as found by Europe PMC text mining. Sharing a sentence is not in itself a finding about the gene and the disease. The quoted sentences say what the papers report.
glioblastoma (10 papers, 2013 to 2025). The most malignant astrocytic tumor (WHO grade IV). "Ceramides play a critical role in the tumorigenesis processes in glioblastoma and the higher expression of SLC27A3 is associated with a worse prognosis." (PMID 37239243, 2023). "Pan-cancer analysis revealed that SLC27A3 was overexpressed in lipid-rich tumors such as ccRCC and glioblastoma." (PMID 39600540, 2024). "SLC27A3 is essential in the stemness and self-renewal of glioblastoma stem cells, as well as in the proliferation and anchorage-independent growth of glioma cells." (PMID 37239243, 2023). "The results of this study have shown that the expression of SLC27A3 was higher in the glioblastoma tumors of men than of women." (PMID 37239243, 2023). "Among the other SLC27, a positive correlation of SLC27A3 expression was found between all studied regions of glioblastoma." (PMID 37239243, 2023). "Additionally, SLC27A3 plays a crucial role in tumorigenesis and cancer progression, as exemplified in glioma, lung cancer, and glioblastoma." (PMID 39600540, 2024). "Furthermore, the expression of SLC27A3 in men was positively correlated with the expression of ELOVL1 in this region of the glioblastoma tumor." (PMID 37239243, 2023). "In addition, a positive correlation was found between the expression of SLC27A1 and SLC27A3 in the glioblastoma tumor and between the expression of SLC27A1 and SLC27A4 in the tumor core." (PMID 37239243, 2023). "Furthermore, SLC27A3 is involved in the tumorigenesis of glioblastomas, particularly in the functioning of glioblastoma stem cells." (PMID 37239243, 2023). "However, comparing the highest and lowest quartiles of SLC27 expression, a trend towards worse outcomes with higher expression of SLC27A4 (p = 0.062) and SLC27A3 (p = 0.083) was observed for glioblastoma patients." (PMID 37239243, 2023). "Only two SLC27 genes, SLC27A3 and SLC27A4, showed a correlation between their expression in the enhancing tumor region and the tumor core of the glioblastoma." (PMID 37239243, 2023). "In glioblastoma tumors, specifically in the tumor core, women exhibit lower expression of SLC27A1 and SLC27A3, but higher expression of SLC27A5 than men." (PMID 37239243, 2023). "We have demonstrated a positive correlation between the expression of SLC27A1 and SLC27A3 and the expression of ELOVL6 in both the glioblastoma tumor and the peritumoral area." (PMID 37239243, 2023). "Similarly to the analysis of all patients, male samples showed a positive correlation of SLC27A1 expression with SLC27A3, SLC27A4 with SLC27A5, SLC27A4 with SLC27A6, and SLC27A5 with SLC27A6 in the studied regions of the glioblastoma tumor." (PMID 37239243, 2023).
glioma (7 papers, 2013 to 2025). A benign or malignant brain and spinal cord tumor that arises from glial cells (astrocytes, oligodendrocytes, ependymal cells). "Functional studies have shown SLC27A3 to be an effective therapeutic target in gliomas because it maintains the oncogenic properties of glioma cell lines through the regulation of the AKT protein." (PMID 23825676, 2013).
diabetes (2 papers, 2019 to 2021). "We discovered several risk-increasing associations with traits related to liver disease, eye disease and cancer, among others, as well as risk-lowering associations for hypertension (SLC9A3R2), diabetes (MAP3K15, FAM234A) and asthma (SLC27A3)." (PMID 34662886, 2021).
malignant glioma (2 papers, 2013). A grade III or grade IV glioma arising from the central nervous system. "Interestingly, SLC27A3 RNA is elevated in malignant glioma cells, and its knockdown inhibits their proliferation." (PMID 23696731, 2013).
Obesity (2 papers, 2021 to 2022). Accumulation of substantial excess body fat. "Both perilipin 2 (PLIN2) and long-chain fatty acid transport protein 3 (SLC27A3) were found to be downregulated in myotubes from donors with obesity." (PMID 36467688, 2022). "However, the role of Slc27a3 in obesity, if any, remains unclear." (PMID 33570456, 2021). "Lastly, the molecular function of Slc27a3 in fatty acid uptake and metabolism in VAT during the progression of obesity remains to be elucidated." (PMID 33570456, 2021).
asthma (1 paper, 2021). "The second novel association was between lower risk of childhood asthma and a burden of rare pLOF and deleterious missense variants in SLC27A3 (3,787 carriers; OR = 0.65, 95% CI 0.55 to 0.76, P = 8.2 × 10−8), which was supported by the following additional observations." (PMID 34662886, 2021).
brain cancer (1 paper, 2024). A primary or metastatic malignant neoplasm affecting the brain. "Very little is known about the importance of SLC27A3 for cell function, but it is overexpressed in human lung and brain cancers." (PMID 39456882, 2024).
Hypercholesterolemia (1 paper, 2020). An increased concentration of cholesterol in the blood. "We also found altered DNA methylation in patients with hypercholesterolemia, in key genes associated with fatty acid transport and metabolism (hypomethylated: PPARD, PPARG, SLC27A1, SLC27A3 and SLC25A20, and hypermethylated: ANGPTL4, ACLS6, ACADM and CPT1A)." (PMID 33028190, 2020).
Insulin resistance (1 paper, 2021). Increased resistance towards insulin, that is, diminished effectiveness of insulin in reducing blood glucose levels. "We propose that increased expression of Slc27a3 by CD in VAT reflects a greater capacity to flux fatty acids across the plasma membrane, leading to adipocyte hypertrophy and insulin resistance." (PMID 33570456, 2021).
Kidney Clear Cell Carcinoma (1 paper, 2024). "By overlapping TCGA (The Cancer Genome Atlas)–KIRC (Kidney Clear Cell Carcinoma) up-regulated genes and RNA sequencing data from 786-O and 786-O-PR, SLC27A3 was selected based on its marked differential expression related to lipid metabolism and its crucial role in ccRCC." (PMID 39600540, 2024).
pulmonary fibrosis (1 paper, 2025). Chronic progressive interstitial lung disorder characterized by the replacement of the lung tissue by connective tissue, leading to progressive dyspnea, respiratory failure, or right heart failure. "Additionally, these results also suggest the possible association between the specifically co-expressed genes such as Ccl22, Asgr2, and Slc27a3, and pulmonary fibrosis." (PMID 40269953, 2025).
schizophrenia (1 paper, 2026). A major psychotic disorder characterized by abnormalities in the perception or expression of reality. "Similarly, SLC27A3 expression in the brain showed significant associations with MD, λ2, and λ3 of the right ICP, in addition to schizophrenia." (PMID 41522603, 2026).
tumor (12 papers, 2013 to 2024). "The tumor specificity of SLC27A3 in ccRCC is an important prerequisite for the development of targeted drugs." (PMID 39600540, 2024). "The differential expression of SLC27A3 and its effect on drug resistance of ccRCC tumor were detected in vitro and in vivo." (PMID 39600540, 2024). "Both paired and unpaired analyses of KIRC-TCGA revealed elevated SLC27A3 expression in tumor samples." (PMID 39600540, 2024). "In the presence of pazopanib, an obvious decrease in tumor luciferase activity was observed in the SLC27A3 knockdown group, accompanied by a reduction in tumor size." (PMID 39600540, 2024). "IHC data demonstrated that SLC27A3 knockdown resulted in weaker tumor proliferation ability in the presence of pazopanib." (PMID 39600540, 2024). "Consistently, SLC27A3 protein levels were increased in clinical tumor samples compared to adjacent normal tissues from 11 ccRCC patients and in cell lines." (PMID 39600540, 2024). "For example, a positive correlation was found between SLC27A3 in the enhancing tumor region and SLC27A1 in the tumor core, and between SLC27A4 in the peritumoral area and SLC27A6 in the tumor core." (PMID 37239243, 2023). "Women also showed a negative correlation between the expression of SLC27A1 in the peritumoral area and the expression of SLC27A3 in the tumor core." (PMID 37239243, 2023). "In men, a positive correlation was observed between the expression of ELOVL1 and SLC27A1, and SLC27A3 in the tumor core." (PMID 37239243, 2023). "In men, there was a negative correlation between the expression of SLC27A5 and a positive correlation between the expression of SLC27A3 with age in the enhancing tumor region." (PMID 37239243, 2023). "The results showed that SLC27A1 and SLC27A3 were higher-expressed in tumor samples of both sets, while SLC27A2, SLC27A4, and SLC27A5 expressions were much lower." (PMID 35927229, 2022). "There was a correlation of SLC27A3 expression between the enhancing tumor region and tumor core." (PMID 37239243, 2023). "However, in the enhancing tumor region (p = 0.04) and tumor core (p = 0.017), the expression of SLC27A3 was lower in female patients than in male patients." (PMID 37239243, 2023). "A negative correlation was found between SLC27A1 in the peritumoral area and SLC27A6 in the tumor core, between SLC27A3 in the enhancing tumor region and SLC27A5 and SLC27A6 in the tumor core, and between SLC27A3 in the tumor core and SLC27A5 in the peritumoral area." (PMID 37239243, 2023). "Furthermore, SLC27A3 expression was positively correlated with ELOVL6 expression in the enhancing tumor region and tumor core." (PMID 37239243, 2023). "Additionally, the expression of SLC27A3 in the enhancing tumor region of men was positively correlated with the age and BMI of the patient." (PMID 37239243, 2023). "Specifically, a positive correlation was observed between SLC27A3 and age in the enhancing tumor region, and a negative correlation was observed with SLC27A5." (PMID 37239243, 2023). "A positive correlation was observed between the expression of SLC27A1 and SLC27A3 in the enhancing tumor region, while a negative correlation was found with the expression of SLC27A4, SLC27A5, and SLC27A6." (PMID 37239243, 2023). "There was also a negative correlation between SLC27A3 expression in the enhancing tumor region and SLC27A5 in the peritumoral area." (PMID 37239243, 2023). "Negative correlations were observed between SLC27A3 and SLC27A4 in the enhancing tumor region and between SLC27A1 and SLC27A5 in the tumor core." (PMID 37239243, 2023). "Women also showed a negative correlation in the expression of SLC27A3 in the peritumoral area with the expression of SLC27A4, SLC27A5, and SLC27A6 in the enhancing tumor region." (PMID 37239243, 2023).
cancer (8 papers, 2013 to 2024). A tumor composed of atypical neoplastic, often pleomorphic cells that invade other tissues. "The role of SLC27A3 in cancer has been investigated only in glioma and lung cancer, evidencing that it was highly expressed in both diseases." (PMID 36556492, 2022). "Among these APAs, 5 APAs (INTS4, SLC27A3, BCCIP, PLK3, HR) were differentially expressed in CRC tissues, when compared with para-cancer tissues." (PMID 35487956, 2022).
infection (2 papers, 2013). The state of being infected such as from the introduction of a foreign agent such as serum, vaccine, antigenic substance or organism. "The siRNA screen and RNA expression analysis revealed roles for a subset of long chain acyl-CoA synthetases following infection: SLC27A6 and ACSL1 were both siRNA hits and increased at the mRNA level, and SLC27A3 was an siRNA hit but not increased in mRNA abundance." (PMID 23696731, 2013).
SLC27A3 also shares sentences with these, for which no sentence is quoted: lung carcinoma (5 papers); breast carcinoma (3); adenocarcinoma (1); atherosclerosis (1); autism (1); brain tumor (1); colon cancer (1); COVID-19 (1); craniosynostosis (1); hepatoma (1); Hypertension (1); large cell carcinoma (1); liver disease (1); lung adenocarcinoma (1); melanoma (1); neurodegenerative disease (1); non-small cell carcinoma (1); polio (1); small cell carcinoma (1); squamous cell carcinoma (1); steatosis (1).